KCNJ10 (potassium inwardly rectifying channel subfamily J member 10)
Diseases named in the same sentence as KCNJ10 in open-access papers (continued):
Sharing a sentence is not in itself a finding about the gene and the disease.
Ataxia (64 papers, 2011 to 2026). Ataxia refers to impaired coordination of voluntary muscle movement. "Homozygous or compound heterozygous pathogenic variants in the KCNJ10 gene cause the SeSAMES syndrome, which features seizures, sensorineural deafness, ataxia, impaired intellectual development, and electrolyte imbalance (OMIM #612780)." (PMID 40121402, 2025). "Mutations of KCNJ10 encoding the Kir4.1 channel leads to epileptic seizures, ataxia, sensorineural hearing loss and renal tubulopathy (EAST syndrome)." (PMID 41465576, 2025). "In the Belgian Malinois breed, a KCNJ10 variant is reported to cause progressive spinocerebellar ataxia (SCA)." (PMID 39473196, 2024). "A third KCNJ10 variant (c.986T>C) causing ataxia is reported in dog breeds unrelated to Terriers, such as Malinois dogs and Bouvier des Ardennes, further strengthening the association between variants in this gene and spinocerebellar ataxia." (PMID 37905444, 2023). "The clinical manifestation of myokymia and neuromyotonia in those 4 dogs was identical to myokymia and neuromyotonia that occurs in association with ataxia in dogs biallelic for the KCNJ10 variant." (PMID 37905444, 2023). "We now also report the KCNJ10 c.627C>G variant causing spinocerebellar ataxia in the Dachshund breed." (PMID 37905444, 2023). "All 21 dogs with spinocerebellar ataxia with myokymia or neuromyotonia were biallelic (homozygous) for the KCNJ10 c.627C>G variant (19 Jack Russell terriers, 1 Dachshund and 1 mixed breed)." (PMID 37905444, 2023). "Variants in KCNJ10 are widely reported to explain spinocerebellar ataxia in affected dogs, a variant in another gene, CAPN1 (c.344G>A), is reported in Parson Russell terriers presenting with spinocerebellar ataxia without myokymia, neuromyotonia or epilepsy." (PMID 37905444, 2023). "Twenty‐four Jack Russell terriers, 1 Jack Russell terrier cross, 1 Dachshund and 1 mixed breed with spinocerebellar ataxia were biallelic (homozygous) for the KCNJ10 c.627C>G variant." (PMID 37905444, 2023). "Most dogs presenting with clinically overt myokymia and neuromyotonia had concurrent spinocerebellar ataxia (84%, 21/25), with all of those dogs being biallelic for the reported KCNJ10 variant." (PMID 37905444, 2023). "KCNJ10 c.627C>G variant is linked to Jack Russell and Parson Russell terriers with spinocerebellar ataxia." (PMID 37905444, 2023). "Underscoring the relative importance of this channel, knockout or mutation of KCNJ10 causes seizures, ataxia, and developmental deficits in mice and humans alike." (PMID 29464197, 2018). "We studied ataxias in the Belgian Shepherd breed and recently reported a candidate causative variant in the KCNJ10 gene for spongy degeneration with cerebellar ataxia, subtype 1 (SDCA1)." (PMID 28620085, 2017). "Recently, we genetically characterized a hereditary cerebellar ataxia in the Belgian Shepherd breed caused by a pathologic variant in KCNJ10, encoding the astrocytic Kir4.1 potassium channel." (PMID 28620085, 2017). "Recently, the missense mutation KCNJ10:c.627C > G was shown to be associated with the spinocerebellar ataxia (SCA) in JRT and related Russell group of terriers, whereas the missense mutation CAPN1:c.344G > A was associated with late onset ataxia (LOA) in PRT." (PMID 27724896, 2016). "In JRT, PRT and related breeds, the missense mutation c.627C > G in the KCNJ10 (potassium inwardly-rectifying channel, subfamily J, member 10) gene (Transcript XM_545752.4) was found to be strongly associated with spinocerebellar ataxia (SCA)." (PMID 27724896, 2016). "This KCNJ10 variant was identified screening a whole-genome sequence of a single JRT with spinocerebellar ataxia and myokymia under the assumptions of an autosomal recessive inheritance and a mutation altering the protein structure." (PMID 27724896, 2016).
Ataxia (continued). "A KCNJ10 mutation, previously associated with an autosomal recessive spinocerebellar ataxia in Jack Russell Terriers, Parson Russell Terriers, and Russell Terriers segregates in at least three more breeds descended from British hunting terriers." (PMID 25998802, 2015). "Although clinical myokymia and neuromyotonia was common in dogs with spinocerebellar ataxia and biallelic for the KCNJ10 variant (21 out of 27 dogs in this study, 78%), a proportion of such dogs (6 out of 27 dogs, 22%) did not have signs of myokymia and/or neuromyotonia." (PMID 37905444, 2023). "The KCNJ10 c.627C>G variant was confirmed to be the causal variant in nearly all affected dogs with clinical signs of spinocerebellar ataxia, except for 1 dog in which the CAPN1 variant was detected and another dog for which the diagnosis remains unknown." (PMID 37905444, 2023). "Although robustly down-regulated at this developmental time point by differentiating excitatory cortical neurons, we note that deficiency in KCNJ10 produces seizures, sensorineural deafness, ataxia, mental retardation, and electrolyte imbalance (SeSAME syndrome)." (PMID 22852769, 2012). "Recessive pathogenic variants in the KCNJ10 gene have been described in homozygous and compound heterozygous state in patients with a complex syndrome comprising seizures, sensorineural deafness, ataxia, impaired intellectual development and electrolyte imbalance (SESAME or EAST syndrome)." (PMID 40426046, 2025). "– Kcnj10-/- : displays severe motor deficits, ipomyelinization in the spinal cord, severe spongiform vacuolation and damaged astrocytes.– cKO gfa2 directed: displays pronounced body tremor, lethargy and ataxia as well as visual placing deficiency and stress induced seizures." (PMID 25784856, 2015). "Mutations in the KCNJ10 gene encoding Kir4.1 have been reported to cause SeSAME/EAST syndrome characterized by early onset seizures, ataxia and mental retardation." (PMID 38678030, 2024). "The KCNJ10 c.627C>G variant, or rarely the CAPN1 c.344G>A variant, was confirmed to be the causal variant of spinocerebellar ataxia." (PMID 37905444, 2023). "This study aims to clarify the potential association between variants in KCNJ10 and CAPN1 genes and myokymia and neuromyotonia in a cohort of 33 dogs with spinocerebellar ataxia, myokymia/neuromyotonia, or both." (PMID 37905444, 2023). "A number of studies have shown that mutations in KCNJ10 are associated with SeSAME/EAST syndrome, which is characterized by seizures, ataxia, sensorineural deafness, and electrolyte imbalance." (PMID 31781151, 2019). "Both Kcnj10-cKO lines exhibited progressive neurological symptoms including abnormal gait and ataxia, generalized seizures and hindlimb clasping starting as early as three months of age." (PMID 30204081, 2018). "KCNJ10 knockout mice present with profound ataxia and late stimulus-sensitive seizures, with early mortality." (PMID 23924083, 2013). "Specifically, loss-of-function mutations in human Kir4.1 gene (KCNJ10) cause the EAST syndrome, including GTC seizures and ataxia." (PMID 23922547, 2013). "KCNJ10 and CAPN1 variants cause “spinocerebellar” ataxia in dogs, but their association with generalized myokymia and neuromyotonia remains unclear." (PMID 37905444, 2023). "The only Parson Russell terrier, also suffering from spinocerebellar ataxia, did not carry this KCNJ10 variant, but was biallelic for the CAPN1 c.344G>A variant." (PMID 37905444, 2023). "Gain-of-function as well as loss-of-function mutations in the human KCNJ10 gene encoding Kir4.1 have been linked to forms of childhood epilepsies associated with ataxia and cognitive impairment, but not to CAE." (PMID 34177766, 2021). "Biallelic loss-of-function variants in KCNJ10 (Kir4.1) have previously been reported to cause SESAME syndrome, which presents with onset of seizures in infancy, ataxia, sensorineural hearing loss, persistent hypokalemia, metabolic alkalosis, and hypomagnesemia." (PMID 33840812, 2021).
Ataxia (continued). "Therefore, we consider KCNJ10:c.986T>C the most likely candidate causative variant for one subtype of SDCA in Malinois dogs, which we propose to term spongy degeneration with cerebellar ataxia 1 (SDCA1)." (PMID 28007838, 2017). "In addition, dogs presenting only with myokymia or neuromyotonia (without ataxia) did not carry the reported KCNJ10 or CAPN1 variants (4 dogs)." (PMID 37905444, 2023). "In addition, 6 of the 7 Jack Russell terriers (including 1 Jack Russell terrier cross) had spinocerebellar ataxia without myokymia or neuromyotonia were biallelic for this KCNJ10 variant." (PMID 37905444, 2023). "Similarly, astrocyte-specific deletion of Kcnj10 using GFAP-cre mice results in premature lethality, epileptic seizures, and severe ataxia, none of which were observed with Kir4.1 deletion using Fabp7-CreER2 mice." (PMID 35997251, 2022).
EAST syndrome (50 papers, 2011 to 2026). "EAST syndrome is caused by mutations in KCNJ10, which encodes Kir4.1, a potassium channel that is expressed in the DCT, brain, and inner ear." (PMID 35195759, 2022). "The importance of basolateral K+ channels is also reinforced by clinical data that identify loss of function mutations in KCNJ10 (Kir4.1) causing EAST/SeSAME syndrome, in which patients have hypokalemia, hypomagnesemia, and salt‐wasting." (PMID 34665521, 2021). "Whole exome sequencing analysis of four patients and two unaffected parents identified a novel missense mutation in KCNJ10, a candidate gene in SeSAME syndrome." (PMID 31640787, 2019). "The most frequent mutation of KCNJ10 in patients with EAST/SeSAME syndrome was Arg65Pro at the cytoplasmic end of the TM-1 domain." (PMID 29358904, 2017). "The mutation of the KCNJ10 gene encoding Kir4.1 conveys the EAST/SeSAME syndrome manifesting GTCS in the early postnatal stage (2–3 months after birth)." (PMID 29358904, 2017). "This study provides evidence that the EAST syndrome caused by KCNJ10 p.R65P mutation in Pakistani patients is likely to be the result of a founder mutation that occurred around 500 years ago." (PMID 27652280, 2016). "EAST syndrome is an autosomal recessive disorder caused by loss‐of‐function mutations in the gene KCNJ10." (PMID 27652280, 2016). "In the case of KCNJ10, the prognosis of patients suffering from EAST/SeSAME syndrome is related to the severity of the mutation causing the disease, with the patients with truncating mutations of KCNJ10 associated with more severe outcomes both in tubulopathy severity and neurological symptomology." (PMID 39414394, 2024). "Indeed, mutations and variations of the KCNJ10 gene encoding for Kir4.1 occur in seizure susceptible human and animal models including the SeSAME/EAST syndrome." (PMID 32019062, 2020). "Mutations in KCNJ10, which encodes human Kir4.1, causes SeSAME/EAST syndrome." (PMID 33381506, 2020). "Therefore, how and why certain KCNJ10 variants fail to manifest electrolyte imbalance in SeSAME syndrome needs to be explored." (PMID 31640787, 2019). "Frequent mutations of KCNJ10 in the EAST/SeSAME syndrome were R65P at the cytoplasmic end of the TM-1 region, G77R at TM-1, C140R at an extracellular loop between TM-1 and TM-2, T164I, and A167V at the cytoplasmic end of TM-2, R175Q, R199X, and R297C at the C-terminal domain." (PMID 30356026, 2018). "– KCNJ10 loss-of-function mutations: cause EAST or SeSAME syndrome." (PMID 25784856, 2015). "For instance, mutations in the CLCNKB gene, which causes Type 3 Bartter syndrome, or in KCNJ10, responsible for EAST (or SeSAME) syndrome, can result in nearly identical lab findings." (PMID 40777730, 2025). "Similar symptoms are seen in patients with SeSAME- or EAST-syndrome, who carry frame-shift or missense mutations in the coding sequence of KCNJ10, the human ortholog of the Kir4.1 gene." (PMID 38032389, 2024). "KCNJ10 mutations are often associated with SeSAME syndrome including salt retention deficits in tubules that express Kir4.1.24,25 However, the HR patients had no reported signs of kidney dysfunction as in multiple sclerosis in general." (PMID 36910419, 2023). "It is still not understood why not all dogs biallelic for KCNJ10 variants develop myokymia or neuromyotonia and why myokymia or neuromyotonia is not reported in humans with EAST syndrome." (PMID 37905444, 2023). "Abnormal frequency of spontaneous contractions was rescued upon co-injection of human KCNJ10 mRNA, but not with human mRNA containing a mutation associated with EAST syndrome." (PMID 33917666, 2021). "This “twitching” reverted to normal levels when human WT cRNA was co-injected, but not KCNJ10 R65P, a missense mutation causing EAST syndrome in humans." (PMID 24244558, 2013).
EAST syndrome (continued). "The data on Kir4.1 localization and function in β2−/−/γ3−/− mice are of special interest because a number of recent articles demonstrated the involvement of mutations of the KCNJ10 gene in human disorders, such as the EAST syndrome." (PMID 21283711, 2011). "Moreover, novel loss-of-function mutations (I60T, I60M, G163D, R171Q, A201T, I209T, and T290A) in KCNJ10 were identified in patients with atypical EAST/SeSAME syndrome lacking one or more core clinical manifestations." (PMID 33424762, 2020).
depression (23 papers, 2018 to 2026). "Kcnj10 encodes a potassium rectifier, Kir4.1, that is involved in maintaining potassium homeostasis and has been implicated in several diseases, including Huntington’s disease, ALS, and depression." (PMID 36291186, 2022). "For example, a postmortem study of 13 patients with depression and 10 healthy controls identified downregulation of KCNJ10 in the hippocampus, although it remained unclear whether this reduction was a causative factor or a consequence of the depressive state." (PMID 40001468, 2025). "Among the large number of astrocyte proteins acting at the tripartite synapse, recent evidence has focused on the inward rectifier potassium channel 4.1 (Kir4.1 channel; KCNJ10 gene) as a possible contributor to several neuropsychiatric diseases, including depression." (PMID 34685608, 2021).
deafness (21 papers, 2004 to 2025). An inherited or acquired condition characterized by the complete loss of the ability to hear from one or both ears. "Less positive EP, potentiated by a reduction of endolymphatic [K+] in Kcnj10−/− mice, reduces the driving force for K+ entry through transduction channels and is sufficient to cause deafness." (PMID 38838775, 2024). "In human patients, KCNJ10 missense or nonsense mutations lead to electrolyte imbalance, seizures, and deafness, which are recapitulated in Kcnj10−/− knockout mice." (PMID 36835631, 2023). "Suppression of the KCNJ10 K+ channel in strial intermediate cells, which is essential for the generation of the endocochlear potential, is probably the direct cause of deafness in Slc26a4-/- mice and patients suffering from Pendred syndrome." (PMID 15320950, 2004). "In addition, we identified potentially novel deafness-associated genes Mpzl2 in IMCs and Tbx1 in MCs along with the known deafness-associated genes in IMCs (Kcnj10, Met, Mitf, Gjb6, Ednrb, and Gjb2) and in MCs (Kcnq1, Esrrb, Kcne1, Lrp2, Slc22a4, and Hgf)." (PMID 37322474, 2023). "It has been reported that EVA might also be caused by the heterozygote of SLC26A4 and FOXI1, or double gene inheritance of SLC26A4 and KCNJ10, which is the first example where double gene inheritance has been proven to be the cause of deafness in human beings." (PMID 34276761, 2021). "Protein expression studies in SLC26A4 knockout mice have indicated that the absence of pendrin expression reduces KCNJ10 protein levels, supporting the hypothesis that deafness in the mouse model is secondary to loss of KCNJ10 function." (PMID 24860705, 2014). "Two other genes, Transformation/Transcription Domain Associated Protein (TRRAP) and Potassium Inwardly Rectifying Channel Subfamily J Member 10 (KCNJ10), have been associated with deafness in humans." (PMID 32413090, 2020).
Huntington disease (21 papers, 2015 to 2025). Huntington disease (HD) is a rare neurodegenerative disorder of the central nervous system characterized by unwanted choreatic movements, behavioral and psychiatric disturbances and dementia. "Alteration of KCNJ10 gene expression is related to neuropathies, such as Huntington's disease East/SeSAME syndrome, by elevating the extracellular K(+), which consequently leads to abnormal neuron excitability." (PMID 35492305, 2022). "Interestingly, though mutations in KCNJ10 have not been linked to neurodegenerative disorders, analysis of animal models of AD, amyotrophic lateral sclerosis (ALS), and Huntington’s disease suggest that downregulation of Kir4.1 in astrocytes may contribute to disease onset and/or progression." (PMID 33381506, 2020).
glioma (20 papers, 2012 to 2025). A benign or malignant brain and spinal cord tumor that arises from glial cells (astrocytes, oligodendrocytes, ependymal cells). "The TRPV2 interactome showed a high association with early glia-related neoplasms, especially glioma/glioblastoma, being ABR, FGF1, KCNJ10, PEBP1, PLP1, SDC3, and TRPV2, the genes associated to these brain neoplasms." (PMID 29719613, 2018). "KCNJ10 was demonstrated as overexpressed in glioma cells and promoted cell differentiation and inhibited growth in gliomas." (PMID 27713134, 2016). "It has been reported that KCNJ10, KCNA5, and KCNN4 can affect the proliferation and invasive ability of gliomas and glioblastomas by altering the cell membrane potential in excitatory cell-derived tumors." (PMID 38905316, 2024). "MiR-5096, as a potential target of the KCNJ10 gene, can decrease Kir4.1 channel protein expression in GBM cells, and miR-5096 and Kir4.1 knockdown can increase glioma cell invasiveness." (PMID 36703789, 2022). "Kir4.1 (KCNJ10) is expressed in glial cells but tends to be absent or mislocalized in gliomas." (PMID 36768856, 2023).
hearing loss (13 papers, 2009 to 2026). "Pathogenic variants in the SLC26A4, FOXI1, and KCNJ10 genes are associated with hearing loss (HL) and specific inner ear abnormalities (DFNB4)." (PMID 36499699, 2022). "Additional findings of double heterozygous mutations associated with hereditary hearing loss have been reported for KCNJ10 and SLC26A4 and for FOXI1 and SLC26A4, and some mutated genes may have a modifying effect." (PMID 24164807, 2013). "In the SV, mutated genes related to ion channels and their regulatory subunits (e.g., KCNE1, KCNQ1 and KCNJ10) may lead to hearing impairment." (PMID 40600354, 2026). "Additionally, other genes such as the CEVA haplotype, FOXI1, KCNJ10, POU3F4, and possibly GJB2 are implicated in 50 %–60 % of cases of hearing loss and enlargement." (PMID 39481243, 2024). "We completed KCNJ10 mutation screening in 133 normal-hearing control subjects with no family history of hereditary hearing loss." (PMID 25372295, 2014). "In our study, we identified a variant of uncertain significance p.P101T in the KCNJ10 gene along with a likely pathogenic variant p.D754Ifs*5 in the SLC26A4 gene and a shortened CEVA haplotype, which involved only three SNPs in a proband with hearing impairment and EVA." (PMID 40426046, 2025).
multiple sclerosis (12 papers, 2007 to 2025). A progressive autoimmune disorder affecting the central nervous system resulting in demyelination. "We tested polymorphisms from the KCNJ9, KCNJ10 and FasL genes (markers that had previously been tested in a number of other genetic disorders, including Multiple Sclerosis (MS))." (PMID 17727731, 2007). "The extracellular e1 sequence of KCNJ10, the inwardly rectifying potassium channel 4.1, has been subject to fierce debate for its role as a candidate autoantigen in multiple sclerosis." (PMID 36910419, 2023).